ENSG00000289503 (novel protein)
Gene: Protein-coding gene on chromosome 14 (62,075,340 to 62,128,421, forward strand). Ensembl gene ENSG00000289503.
Genetic constraint (gnomAD): Missense variants: 43 observed, 47.36 expected, observed/expected ratio (o/e) 0.91, 90% interval 0.71 to 1.17. Synonymous variants: 15 observed, 15.83 expected, observed/expected ratio (o/e) 0.95, 90% interval 0.63 to 1.46.